INS (insulin)
Diseases named in the same sentence as INS in open-access papers (continued):
Sharing a sentence is not in itself a finding about the gene and the disease.
Hyperglycemia (continued). "Hyperglycemia observed at W1 of lactation could be ascribed to the low responsiveness of peripheral tissues to insulin." (PMID 34840462, 2021). "Hyperglycemia, including impaired fasting plasma glucose and DM, was found to be associated with non-dippers because hyperinsulinism in an insulin-resistant state causes sodium retention and alteration of arterial structure and function." (PMID 34776006, 2021). "Lastly, our study could not fully address the question of adequate blood glucose level or whether treatment of hyperglycemia with insulin may reduce the incidence of MINS or mortality." (PMID 34830501, 2021). "In STZ induced hyperglycemic mice model, PGLP-1-VP ameliorates STZ-induced hyperglycemia and improves insulin sensitivity, which indicates that PGLP-1-VP could work as a long-acting GLP-1R agonist in vivo." (PMID 33574570, 2021). "INS treatment is also one potential strategy for alleviating postprandial hyperglycemia." (PMID 33809008, 2021). "As ACE2 expression is particularly amplified in key metabolic organs such as the liver, adipose tissue, and the small intestine, SARS-CoV-2 may attack these organs, resulting in insulin insensitivity and an exacerbation of hyperglycemia." (PMID 34690930, 2021). "We also observed that the extreme osmolarity increase associated with extreme hyperglycemia does not appear to negatively impact insulin secretion, at least in our in vitro studies in mouse islets." (PMID 34205432, 2021). "Time in hyperglycaemia and basal insulin requirements decreased significantly." (PMID 34277978, 2021). "Furthermore, the inability of puppies to recover quickly from hypoglycaemia or hyperglycaemia can be attributed to their insensitivity to endogenous insulin and the low response of counterregulatory hormones (epinephrine and cortisol)." (PMID 34362371, 2021). "According to GRASP (Glucose regulation in acute stroke patients) and THIS (Treatment of hyperglycemia in ischemic stroke) trials, intensive glucose control through the use of insulin in patients with acute ischaemic stroke is both safe and results in better control." (PMID 34640636, 2021). "Within this context, lifestyle interventions, such as optimal regulation of body weight and increased physical activity/exercise, are important to improve the sensitivity of tissues to insulin, and hence avoid marked hyperglycemia and hyperinsulinemia under fasting or postprandial conditions." (PMID 33419065, 2021). "On the other hand, hyperglycemia induces insulin secretion from Langerhans islets in the pancreas." (PMID 34024765, 2021). "In addition, HNF1A is required for insulin secretion, in line with hyperglycemia observed in patients." (PMID 34079523, 2021). "The gene-level analysis showed that WT obese RvE1 treated mice had significantly upregulated genes in pathways relating to insulin sensitivity, which corroborates our previous findings that established RvE1's effects at reducing hyperinsulinemia and hyperglycemia." (PMID 35004828, 2021). "The present study demonstrates that CPE’s antidiabetic, antioxidant, and renoprotective effects involve improved hyperglycemia, lipid profiles, insulin resistance, visceral fat deposition, lipid peroxidation, renal lipid accumulation, and cationic transport function." (PMID 33800673, 2021). "Furthermore, their blood levels of glucose, insulin, cholesterol, and C-reactive protein were significantly higher confirming that db/db mice developed hyperglycemia, dyslipidemia and inflammation." (PMID 33546276, 2021). "Transoperative stress hyperglycemia is a common clinical finding due to a transient decrease in insulin responsiveness that may persist from days to weeks after major surgery." (PMID 34141709, 2021). "Finally, LCN2 can control metabolic homeostasis, including insulin sensitivity, hyperglycemia, and dyslipidemia through the modulation of NF‐κB, C/EBP signaling, HbA1c level, and body fat mass." (PMID 33945675, 2021).
Hyperglycemia (continued). "Third, patients with severe hyperglycemia required long-term external insulin treatment." (PMID 34283877, 2021). "As to other antidiabetic agents, glucagon receptor peptide‐1 (GLP‐1) receptor agonists and dipeptidyl peptidase‐4 inhibitors, which increase endogenous GLP‐1, apparently improve hyperglycemia by acting in pancreas to diminish glucagon secretion and improve glucose‐stimulated insulin secretion." (PMID 34766133, 2021). "We speculate that the fetus is sensing intermittent episodes of maternal hyperglycaemia and adapting through increased production of insulin." (PMID 33833312, 2021). "His hyperglycemia became persistent, requiring insulin therapy at the age of 10 years." (PMID 34373539, 2021). "However, long-term GCs overexposure alters expansion of trunk adipose tissue depots and impairs metabolism and insulin action, resulting in hyperglycemia and dyslipidemia." (PMID 34735568, 2021). "As alluded to above, it remains to be defined whether the hybrid polypeptide binds to the antibodies and may compete with insulin for insulin-receptor binding and thereby contribute to hyperglycaemia." (PMID 34170845, 2021). "Although conventional available treatments, including oral antidiabetes dugs and exogenous insulin injection, can improve hyperglycemia-related symptoms or temporarily improve insulin sensitivity in target tissues, these treatments reverse neither disease progression nor cellular dysfunction." (PMID 34135959, 2021). "Insulin replacement therapy has been the mainstay of treatment for CFRD because it addresses both the protein catabolic state that results from insulin insufficiency, and the pro-inflammatory, pro-infectious state caused by hyperglycemia." (PMID 34926166, 2021). "The analysis of the efficacy of pre-meal insulin or oral antidiabetic agents in controlling postprandial hyperglycemia in CFRD showed that aspart insulin is more effective than repaglinide, and regular insulin is as effective as repaglinide in patients with HbA1c <7%." (PMID 34017312, 2021). "Insulin may be used until hyperglycemia resolves, usually in 1–2 days due to the short half-life of alpelisib." (PMID 34281618, 2021). "We concur with the ADA/EASD guidelines, suggesting flipping the pyramid upside down: most patients should commence with a GLP-1 RA injection and only a minority should start with basal insulin as the first injectable (including patients with symptomatic hyperglycemia and/or HbA1c > 9.0%, as above)." (PMID 33910583, 2021). "Chronic exposure to pro-inflammatory cytokines such as TNF-α, IL-1β and IL-6 activates the signaling proteins that block the activation of the insulin signaling cascade in the target organs of insulin, including skeletal muscle, adipose tissue and liver, leading to hyperglycemia." (PMID 34201653, 2021). "Therefore, the impaired insulin signaling in the gastrocnemius muscles represents a mechanism for the induction of post-ischemic hyperglycemia through TNF-α-mediated IRS1 inhibition, with R-7050 improving this impairment." (PMID 34073455, 2021). "The rates of gastric emptying and intestinal glucose absorption determine the feedback relationship between the increases in blood glucose levels and insulin secretion, and therefore play a decisive role in the magnitude of postprandial hyperglycemia and hyperinsulinemia." (PMID 33419065, 2021). "The peri-pancreatic adipose tissue releases chemokines and VEGF that favor the infiltration of macrophages in the pancreas, immune cells that release cytokines responsible for inhibiting insulin secretion by beta-pancreatic cells and the generation of hyperglycemia in obese subjects." (PMID 34948944, 2021). "Hence, when a sustained elevation of insulin secretion occurs, such as in the case of hyperglycemia, chronic insulin levels will induce cardiomyocytes hypertrophy, which will promote cardiac hypertrophy." (PMID 34835942, 2021).
Hyperglycemia (continued). "HbA1c is a reliable marker of hyperglycemia and may be a suitable marker of chronic hyperinsulinemia, as high glucose levels correspond to high insulin levels." (PMID 34803930, 2021). "Furthermore, hyperglycaemia is exacerbated by the production of insulin antagonists i.e., human chorionic gonadotropin and prolactin during pregnancy, which reach their physiological peaked from 8 weeks gestation onwards." (PMID 34513891, 2021). "In vitro, a co-culture study of rat PSCs with the rat β cell line, RIN-5F showed increased RIN-5F cell apoptosis secondary to caspase activation and depolarisation of mitochondria and inhibition of insulin secretion, suggesting a role for PSCs in inducing hyperglycaemia." (PMID 34680372, 2021). "Our present findings clearly showed that the novel triterpenoid compounds from C. fistula controlled hyperglycemia through activation of IRS-1/Akt-mediated insulin signaling mechanisms and through regulation of carbohydrate metabolic enzymes in the skeletal muscle and liver." (PMID 34833905, 2021). "Hyperglycemia is a term used for high blood glucose level, caused either by a lack of insulin secretion or its inaction." (PMID 34225729, 2021). "It is frequently characterized by onset of hyperglycaemia caused by impairment of insulin secretion, with minimal or no defects in insulin action." (PMID 34496959, 2021). "High birth weight of the baby may be explained by the fact that starting from the second trimester, the pancreas of the baby secretes insulin in response to hyperglycemia, which results in hyperinsulinemia." (PMID 33572044, 2021). "Inflammatory stress interferes with insulin action, resulting in hyperglycemia." (PMID 34073455, 2021). "Interestingly, these AMSCs demonstrated enhanced release of insulin, increased cell proliferation and upregulation of insulin 1, insulin 2, Ngn3, Nkx6.2, and Pdx1when triggered by hyperglycemia." (PMID 33968939, 2021). "Conceivably, cognitive impairment due to persistent hyperglycemia in patients with T2DM may cause changes in bacterial metabolites, which stimulate insulin resistance, resulting in augmentation of Aβ pathology in the brain." (PMID 34485269, 2021). "Thus, the sympathetic response to acute hyperglycaemia and hyperinsulinaemia appears to be impaired in overweight insulin-resistant individuals, perhaps because of adaptation to slightly elevated glucose levels." (PMID 33241460, 2021). "For patients with hyperglycemia, clinical response was defined ad-hoc as ≥0.5% decrease in HbA1c, normalization or ≥50-mg/dL decrease in 2-h plasma glucose value on oral glucose tolerance test, or decrease in daily insulin (≥25%) or sulfonylurea dose (≥50%)." (PMID 34335465, 2021). "Hyperglycaemia in COVID-19 may represent an effect on insulin resistance but it has also been questioned whether insulin production might also be affected." (PMID 34220705, 2021). "In this study, we improved a previous strategy to produce beta cells using extracellular vesicles (EVs) derived from mature beta cells and differentiated beta cells from iPSCs (i-Beta cells), which secreted insulin under glucose stimulation in vitro and ameliorated hyperglycemia in vivo." (PMID 34055806, 2021). "A decrease in insulin concentrations after the induction of anesthesia followed by a stress-induced catabolic hyperglycemia [adrenocorticotropic hormone (ACTH) and cortisol-induced] has been described, but the effects are short-lived with normalization within 24–48 h after surgery." (PMID 33869110, 2021). "After MLDS treatment, those mice showed a lower level of insulin and severe hyperglycemia." (PMID 34621265, 2021). "SGLT-2 inhibitor blocks this mechanism causing reduction of hyperglycemia, independent of insulin and thereby avoiding hypoglycemic episodes." (PMID 34123681, 2021). "HO-1 up-regulation can increase insulin secretion, thereby reducing hyperglycemia." (PMID 34946740, 2021).
Hyperglycemia (continued). "In the presence of normal blood glucose levels, HMGB1 might stimulate insulin release from pancreatic beta cells, which, differently, is inhibited in the presence of hyperglycemia." (PMID 34360753, 2021). "In the process of body glucose balance, insulin resistance affects the expression and activity of glucose transporters, thereby increasing the accumulation of glucose in the circulatory system and forming hyperglycemia." (PMID 34702218, 2021). "To survive, subjects with type 1 diabetes must rely on exogenously injected insulin in subcutaneous tissue: this ensures adequate basal and prandial insulin concentrations to recreate physiological insulin profiles to avoid ketoacidosis and hyperglycemia-related complications." (PMID 33755854, 2021). "The rate of β-cell proliferation in rodents and humans diminishes dramatically with aging, when β-cell mass expansion stalls, insulin resistance increases, β-cell functionality enhances, and the incidence of hyperglycemia, and eventually T2D, is highly increased." (PMID 33239359, 2021). "Hyperthyroidism could promote hyperglycaemia and reduce the half-life of insulin, leading to an increased rate of degradation and an enhanced release of biologically inactive insulin precursors." (PMID 34670571, 2021). "In addition, the treatment of overweight and diabetic rats by administration of pure fiber significantly reduced hyperglycemia, restored insulin sensitivity, resolved fatty liver disease, and increased insulin action in liver tissue." (PMID 34083930, 2021). "In a study from a separate group, quercetin administration (25 mg/kg/day, i.p.)for 33 days beginning 3 days prior to STZ induction in Wistar rats (75 mg/kg, single injection) prevented the onset of hyperglycemia and restored plasma insulin concentrations to control values." (PMID 35098034, 2021). "These factors may also have contributed to the hyperglycemia and reduced insulin sensitivity phenotype we observed." (PMID 34121997, 2021). "Through metabolic regulation, insulin alleviates the harmful effects of hyperglycemia." (PMID 34795562, 2021). "Whey protein may improve hyperglycemia by several mechanisms including stimulation of insulin secretion and the action of incretin hormones such as glucagon-like polypeptide-1 and gastric inhibitory peptide." (PMID 33663466, 2021). "Meanwhile, the serum insulin level in the db/db group was significantly decreased (P<0.01), suggesting that the islet function of 16-week db/db mice had entered the failure stage and hyperglycemia was a probable result of islet beta-cell failure." (PMID 34249264, 2021). "Measurement of the insulin content in isolated islets from Pdia6F175S−/− mice revealed over 80% reduction compared to that of wild-type (WT) mice, corresponding to the undetectable amounts of plasma insulin and acute hyperglycemia in these animals." (PMID 34487921, 2021). "Thus, MSCs derived exosomes ameliorate hyperglycemia via improved insulin sensitivity and β-cell function." (PMID 34163437, 2021). "This observational study highlights the potential detrimental long-term effects of neonatal hyperglycaemia, while the benefit of insulin treatment remains unclear." (PMID 33863775, 2021). "The clinical expression of T2DM usually follows a decrease in the responsiveness (increase in the resistance) to insulin (especially in skeletal muscle, liver, and adipose tissue) and a decrease in insulin secretory response to hyperglycemia by pancreatic β cells." (PMID 34441977, 2021). "However, insulin secretion is seldom tested in hyperglycemia exceeding these levels despite the Guinness World Record being 147.6 mM (2656 mg/dL)." (PMID 34205432, 2021). "Finding a way to help individuals with T2DM to activate the rapid first phase response, i.e., increased insulin, would likely only potentiate the insulin resistance and further increase their hyperinsulinaemia, which is present for a period of time preceding hyperglycaemia." (PMID 34356863, 2021).
Hyperglycemia (continued). "However, kisspeptin stimulates insulin secretion only when glucose levels are elevated, suggesting kisspeptin’s role involves correcting hyperglycemia." (PMID 34300220, 2021). "Furthermore, if hyperglycemia is diagnosed insulin has to be given and severe metabolic acidosis has to be countered by sodium bicarbonate (pH <7.10 or bicarbonate <10 mEq/L)." (PMID 34977106, 2021). "Another study showed that hospitalized patients with hyperglycemia treated with an insulin infusion had a lower risk of death from COVID-19 than patients who did not receive an insulin infusion, most likely due to a decrease in inflammatory mediators." (PMID 34578858, 2021). "Similarly, rats exposed to DEHP throughout gestation and perinatal development exhibited hyperglycemia in the presence of reduced insulin levels along with reductions in β-cell mass, reduced islet insulin content, and disruptions in β-cell ultrastructure." (PMID 34063694, 2021). "DM is a group of metabolic diseases that lead to high levels of glucose (hyperglycemia), which is caused either by insufficient insulin production or a lack of insulin response." (PMID 34970629, 2021). "Hyperglycemia and the need for anti-diabetic treatment (insulin therapy or oral drugs) persisted in 73% of surviving diabetic patients (46/63), whereas anti-diabetic treatment could be stopped in 17 patients (27%)." (PMID 34449740, 2021). "Furthermore, when these mice were fed a high-fat diet to induce hyperglycemia, they again showed improved glucose tolerance, insulin secretion, and insulin sensitivity." (PMID 34582892, 2021). "Thirdly, postprandial hyperglycemia induced by diets high in sugars triggers insulin and insulin-like growth factor I synthesis, which may enhance tumor development through promoting cell proliferation and inhibiting apoptosis." (PMID 33854607, 2021). "Therefore, in this study, we assessed the effect of honey on hyperglycemia, dyslipidemia, oxidative stress and nerve conduction and compared it with insulin treatment in diabetic neuropathy rat models and their association with the complications of DN." (PMID 33449943, 2021). "However, some research had determined that the profuse liberation of catecholamines inhibits insulin secretion and the movement and breaking down of hepatic glycogen, generating hyperglycemia, helping to the myocardial damage." (PMID 34822541, 2021). "Interestingly, insulin infusion to diabetic rats by APS was superior in reducing the duration of hyperglycemia as compared to insulin released from native pancreatic β-cells in healthy rats." (PMID 34270619, 2021). "In addition, it has been reported that PTP-MEG2 is an antagonist of liver insulin signaling and that depletion of PTP-MEG2 in the liver of diabetic (db/db) mice leads to insulin sensitization and normalization of hyperglycemia." (PMID 33799458, 2021). "We further provided both in vitro and in vivo evidence supporting that heparin induces hyperglycaemia by binding with insulin to inhibit the insulin‐dependent downstream cascade PI3K/Akt/GLUT4 signalling pathway, which impairs glucose uptake in skeletal muscle." (PMID 34277977, 2021). "It is unclear for hyperglycemia, whether a basal-bolus of insulin is beneficial compared with a standard sliding scale in the emergency surgical population." (PMID 33677649, 2021). "When insulin signaling is impaired in liver by either insulin resistance or low insulin levels, the glucose storage and production is dysregulated, increasing the hepatic glucose output rates yielding hyperglycemia in diabetic patients." (PMID 35002743, 2021). "Hyperglycemia arises because of β-cell failure to synthesize sufficient insulin." (PMID 33727637, 2021). "However, β-cells can initially compensate for this by increasing insulin release, and it is a subsequent decline in β-cell function that leads to hyperglycemia and overt T2DM." (PMID 34970150, 2021).